CRP (C-reactive protein)
Diseases named in the same sentence as CRP in open-access papers (continued):
Sharing a sentence is not in itself a finding about the gene and the disease.
COVID-19 (continued). "Our data indicate that the mean CRP level is almost three times higher in the “severe” group relative to the “mild” COVID-19 group." (PMID 36555850, 2022). "CRP levels at baseline were significantly higher in the severe and moderate COVID-19 patients compared to those with mild disease and significantly lowered with time/treatment." (PMID 35187271, 2022). "Correlations between NP and CRP, or between NP and IL-6 in COVID-19 patients were weaker than that between CRP and IL-6." (PMID 35529699, 2022). "Severe COVID-19 predictors include elevated serum C-reactive protein, lactate dehydrogenase, and D-dimer." (PMID 36035409, 2022). "Li and colleagues found that the levels of inflammation indicators like CRP, serum ferritin and ESR were increased in COVID-19 patients and associated with the severity of the disease." (PMID 35975270, 2022). "On postnatal age day 11, CRP was raised to 102.1 mg/L, and serum IL-6 was found to be high (13.48 pg/mL), suggestive of post-COVID-19 effects." (PMID 35419241, 2022). "For instance, repeated studies show that levels of CRP are useful as a biomarker to follow COVID-19 progression, and patient management." (PMID 36514048, 2022). "There were also positive correlations with saliva IL-17 level and serum D-dimer, CRP, and ferritin levels of COVID-19 patients (P<0.001)." (PMID 36136963, 2022). "Among patients with moderate COVID-19, more had chronic cardiac and liver diseases and a more important inflammatory syndrome during hospitalization (higher D-dimers, ferritin, and C-reactive protein values)." (PMID 35743970, 2022). "Third, levels of inflammatory biomarkers, especially IL-6 and CRP, show high discriminative accuracy to predict the need for hospitalisation in patients with COVID-19." (PMID 35622838, 2022). "Mid-regional proadrenomedullin has a higher prognostic value in patients with COVID-19 in comparison with routine inflammatory markers (leukocyte and neutrophils levels, CRP, and PCT) and NEWS." (PMID 36072940, 2022). "Severe COVID-19 patients, compared to individuals with moderate illness and healthy controls, had lower lymphocyte counts and increased CRP with greater WBCs counts." (PMID 36675695, 2022). "This conclusion is further supported by the fact that in patients with symptomatic COVID-19, the levels of D-dimer and C-reactive protein (CRP) were about 2.5 and 6 times higher, respectively, compared to pregnant women without SARS-CoV-2 infection." (PMID 35892675, 2022). "Bacterial co-infections due to low immune functions would be another possible reason for explaining the increased levels of NLR and other inflammatory biomarkers, such as CRP and procalcitonin, in COVID-19 patients with severe disease manifestation." (PMID 36090992, 2022). "Evidence suggests that high sensitivity (hs) C-reactive protein (CRP), interleukin (IL)-6, and matrix metalloproteinases (MMPs) are among the most important biomarkers of COVID-19 severity, similar to the chronic conditions involved in vascular aging." (PMID 36296982, 2022). "Because the scientific evidence indicating such a role is inconsistent, we aimed to evaluate the effect of Omega-3 on CRP change and CRP level in patients with COVID-19." (PMID 36064554, 2022). "Among all the laboratory tests, the majority of the respondents (90.80%) mentioned that antibiotics should be prescribed to treat COVID-19 patients only after performing a C-reactive Protein (CRP) test." (PMID 36290008, 2022). "CYP1A2 showed a decrease of 53% during SARS-CoV-2 infection measured in blood samples from 18 COVID-19 patients, with an inverse correlation with interleukin 6 and C-reactive protein levels." (PMID 36052135, 2022). "The elevation of NP levels was supposed to be distinct from those of CRP and IL-6 in relatively early and mild COVID-19 patients." (PMID 35529699, 2022).
COVID-19 (continued). "It is also relevant to consider how the FER biomarker behaves as a specific biomarker for COVID-19, in contrast with the unspecific CRP biomarker in the multiple regression model obtained." (PMID 36140055, 2022). "More recently, CRP/albumin ratios have been proven to be a powerful mortality prognosis marker in hypertensive COVID-19 adults, and systematic research should be performed in order to assess the screening and diagnostic accuracy of this serologic marker." (PMID 36090970, 2022). "Several studies have revealed typical laboratory characteristics in COVID-19 patients, such as elevated levels of C-reactive protein (CRP) and lactate dehydrogenase (LDH), as well as leukocytopenia." (PMID 36532907, 2022). "Baseline CRP has been widely studied as a predictor of COVID-19 severity in the acute phase of the disease." (PMID 35277562, 2022). "C-reactive protein, which is the main inflammatory marker in COVID-19 patients, showed a decrease in the comparison between baseline at 2 months (p = 0.01) and baseline at 4 months (p = 0.01) in the UC-MSC group." (PMID 35313959, 2022). "CRP was a consistent predictor of COVID-19 outcomes in POP2, such that odds of requiring a ventilator (1.07, 1.06-1.08), ICU admission (1.08, 1.07-1.09), and mortality (1.05, 1.04-1.06) were significantly higher." (PMID 36589196, 2022). "In another study of 2782 patients with COVID-19, it was shown that more than 97% of patients had elevated CRP levels on admission; high baseline CRP levels were associated with progression to critical illness, acute kidney injury, VTE, and all-cause mortality." (PMID 36366539, 2022). "Although several factors, including elevated levels of inflammation markers such as C-reactive protein (CRP) and interleukin-6 (IL-6) correlate with severity of COVID-19, the course of severe disease remains highly unpredictable." (PMID 36171547, 2022). "At day 10, a tacrolimus Ctrough of 28.6 μg/L was measured with a CRP level of 515 mg/L, a 630% higher dose-corrected Ctrough during COVID-19 compared to pre-COVID-19." (PMID 35651879, 2022). "Further data on LDH, CRP, and age can be used to identify patients with severe COVID-19 at admission." (PMID 36445863, 2022). "One study reported an improvement in CRP levels following a third dose of the COVID-19 vaccine in patients that were suffering from long-term symptoms after breakthrough infection." (PMID 35883640, 2022). "A total of 85.7% of patients hospitalized with COVID-19 had CRP values > 10 mg/L, 75.5% had fibrinogen values > 400 mg/dL, and 76.8% had D-dimer values > 250 ng/mL." (PMID 35857793, 2022). "The severe disease course was defined by the requirement for oxygen supply, a CRP plasma concentration > 100 mg/L, a poor overall condition and visible COVID-19 infiltrates in the chest X-ray/CT." (PMID 35407564, 2022). "The umbrella review by A Ciapponii including 66 systematic reviews of observational studies related to COVID-19 in pregnancy reported raised CRP in 28%-96%, lymphocytopenia 33.6% to 80% and abnormal radiological findings in 7.1% to 99% cases." (PMID 35261838, 2022). "Patients with COVID-19 in general show increased levels of D-dimers, interleukin-6 (IL-6), C-reactive protein (CRP), fibrinogen, and platelets." (PMID 36142094, 2022). "SII, a less studied ratio, also proved to be significantly increased in non-surviving cases, and all the 11 biochemical parameters studied in our study, especially CRP, are beneficial in assessing COVID-19 progression into mortality." (PMID 36381891, 2022). "g., CRP, Ferritin, D-dimer), although we acknowledge that the COVID-19 patients were recruited from a diverse demographic at two different sites, and included a range of disease stages (days after onset) and severities." (PMID 35947596, 2022). "Only variables with p values of <0.20 in the univariate analysis were included: gender, overweight/obesity, temperature, COVID-19 severity, CRP, D-dimers and endocan." (PMID 36233427, 2022).
COVID-19 (continued). "CRP is a highly soluble protein and a marker of COVID-19 severity and can induce endothelial and smooth muscle cells to express TF." (PMID 35929616, 2022). "The prognostic value of several biomarkers (e.g. CRP, IL-6, ferritin) and clinical scores for predicting disease progression in COVID-19 at early disease stages, e.g. at hospital admission, is now well established." (PMID 36812516, 2022). "Circulating levels of AAT and CRP were elevated (42 ± 12.96, and 178 ± 120.9 respectively) in patients with a diagnosis of COVID-19 compared to Healthy controls." (PMID 36084115, 2022). "A total of 10 variables were found for the characterization of COVID-19: age, sex, anemia, immunosuppression, C-reactive protein, chronic obstructive pulmonary disease, cardiorespiratory disease, metastasis, leukocytes and monocytes." (PMID 35806866, 2022). "Evidence supports the usefulness of biomarkers such as C-reactive protein, troponin, and D-dimer in predicting mortality, disease severity, or thrombotic complications among patients hospitalized for COVID-19." (PMID 35630030, 2022). "In analyses of the cytokine storm severity in COVID-19, most of the trials used the CRP level as a unified marker of inflammation." (PMID 35887283, 2022). "Another study conducted in Wuhan showed significantly higher CRP levels in severe COVID-19 patients than others." (PMID 35281265, 2022). "D-dimer levels increased in patients with COVID-19, being normal in bacterial pneumonia.C-reactive protein (CRP) is used to guide the use of tocilizumab; however, bacterial superinfection must be ruled out." (PMID 36046297, 2022). "The elevated levels of inflammatory markers, including C-reactive protein, ferritin, interleukin-1B, and interleukin-6 represent the signature of a severe COVID-19 phenotype." (PMID 36431059, 2022). "The group with stroke after COVID-19 had lower lymphocyte count and higher CRP, LDH, D-dimer, and fibrinogen." (PMID 36325667, 2022). "COVID-19 patients with DM have significantly higher inflammatory markers, such as interleukin 6 (IL-6), C-reactive protein (CRP), and neutrophil–lymphocyte ratio (NLR) than those without DM." (PMID 36292550, 2022). "To date, only a small study with 24 patients has explored a combination model with IL-6, sKL-6, and CRP values to detect patients with severe COVID-19 with promising results." (PMID 36004366, 2022). "It is worth noting that coagulation abnormalities and pulmonary damages among severe COVID-19 patients, presenting as elevated serum d-dimer and KL-6, continued before discharge, when the median of CRP levels was in the normal range." (PMID 35350784, 2022). "In conclusion, increased CRP, IL-6, KL-6, HMGB-1, and d-dimer levels and decreased platelet counts were associated with the start of mechanical ventilation due to COVID-19." (PMID 35204430, 2022). "The CRP levels at the time of hospitalization were higher in deceased immunocompromised patients compared to the COVID-19-recovered individuals." (PMID 35632677, 2022). "A nomogram for DRM-COVID-19 containing the dyspnea, incubation period, number of comorbidities, D-dimer, CRP, and CT score was constructed." (PMID 35549897, 2022). "Although COVID-19 patients suffer from a viral disease, CRP levels in COVID-19 patients with a bad prognosis are surprisingly high." (PMID 35407379, 2022). "A total of 17 highly correlated variables such as old age, high weight, dry coughs, fever, dyspnea, loss of smell, cardiovascular diseases, hypertension, CRP, ALT/ASP, SPO2, and leukocytosis were selected as the top predictors affecting COVID-19 readmission." (PMID 35596167, 2022). "Our findings are consistent with medical literature data, and several other studies reported higher IL-6 levels in severe COVID-19 cases and higher CRP in correlation with disease severity or adverse outcomes." (PMID 36142336, 2022). "We reasoned that studying the dynamics of CRP by eCRPv would also advance our understanding of the progression of COVID-19." (PMID 36477474, 2022).
COVID-19 (continued). "In the receiver operating characteristic curve, SAA, IL-6 and CRP showed strong sensitivity and specificity in predicting the severity and prognosis of COVID-19." (PMID 35958594, 2022). "We predicted that not only should CRP and D-dimer be considered as predictors of COVID-19 fatal progression, but other parameters should be contemporaneously taken into consideration for early intervention with appropriate treatments." (PMID 35054342, 2022). "Among the routine laboratory parameters, CRP, an acute phase protein, is known to be a strong indicator of COVID-19 severity." (PMID 35242241, 2022). "Multiple studies have corroborated NLR’s to be an independent risk factor for severe COVID-19 and in combination with other markers too such as CRP, it can be a reliable predictor of COVID-19 severity." (PMID 35935776, 2022). "It has been reported that KL-6 levels significantly correlated with other inflammatory biomarkers, such as CRP, neutrophils, and IL-6 levels in COVID-19." (PMID 36295478, 2022). "Elevated levels of IL-6 (and downstream protein CRP) are well-described as signs of poor outcome in COVID-19." (PMID 35386227, 2022). "This genus is also negatively correlated with CRP and procalcitonin levels in patients with COVID-19." (PMID 35310853, 2022). "Elevated levels of CRP and interleukin-6 (IL-6) were observed in AF patients accompanying COVID-19, indicating increased inflammation." (PMID 35796916, 2022). "In our study, mid-regional proadrenomedullin has the highest prognostic value as a predictor of poor outcome in patients with COVID-19, compared to leukocytes and neutrophils levels, C-reactive protein and procalcitonin concentrations." (PMID 36072940, 2022). "The rationale behind was that SARS-CoV-2 infection initiated an unhalted autoimmune response by CRP going along with macrophage and complement activation suspected to be responsible for pulmonary fibrosis and subsequent organ failure in COVID-19." (PMID 35402541, 2022). "The initial and maximum C-reactive protein (CRP) levels were significantly different for COVID-19 survivors compared to fatalities." (PMID 35893707, 2022). "A total of 85.7% of patients hospitalized with COVID-19 had CRP values > 10 mg/L, 76.8% had D-dimer values > 250 ng/mL, and 75.5% had fibrinogen values > 400 mg/dL." (PMID 35857793, 2022). "Serum IP-10, MCP-1, CRP, IFNγ, IL-10, IL-13, IL-17α, IL-23, and IL-6 were significantly higher in COVID-19 patients compared to controls." (PMID 36554094, 2022). "According to the asymptomatic status of COVID-19 in the patient, values of interleukin (IL)-6, IL-8, ferritin, and C-reactive protein were in the normal range." (PMID 35779200, 2022). "Similar, due to the postulated critical role of inflammatory response in severe COVID-19 systematic inflammation factors, CRP, interleukin-6, and interleukin-8, neutrophil-to-lymphocyte ratio are assumed to correlate with clinical outcome." (PMID 35207272, 2022). "Serum DPP4 activity significantly correlated with clinically meaningful parameters in COVID-19, including the patients' ages, absolute lymphocyte count and serum albumin, C-reactive protein, IL-6 and plasma D-dimer levels." (PMID 35195023, 2022). "Higher levels of CRP on admission have been linked to disease progression to a severe form, indicating the potential utility of CRP as an early predictive biomarker for COVID-19 severity." (PMID 36142336, 2022). "IL-1Ra and the P2X7 receptor both increased with the severity of COVID-19 symptoms, but only the P2X7 receptor correlated with CRP concentration in the plasma of COVID-19 patients." (PMID 35663992, 2022). "Hypertension (HTN) (p=0.008), CLD (p=0.02), TLC (p<0.001), NLR (p=0.004), AST (p=0.04), CRP (p=0.005), IL-6 (p=0.02) were associated with need for ICU care among hospitalized COVID-19 patients." (PMID 36060343, 2022).
COVID-19 (continued). "Our results indicate that EMAP-II expression and inflammatory mediators, such as CRP, ferritin, and D-dimers, were significantly correlated in severe COVID-19 patients." (PMID 36560587, 2022). "After adjusting for potential confounders, older age, dyspnea, high CRP, and lymphocytopenia were found to predict oxygen therapy among the COVID-19-infected patients." (PMID 35683357, 2022). "Tocilizumab is a potential therapeutic agent for severe and critically-ill COVID-19 patients; it resulted in clinical improvement of patients, reducing levels of several inflammatory markers including CRP, LDH, and fibrinogen." (PMID 35203844, 2022). "The rapid kinetics of circulating CRP explains why both CRP peak and the velocity of increase have been previously used in the definition of hyperinflammation in COVID-19 patients." (PMID 35277562, 2022). "Vitamin D and CRP had a -0.879 correlation value, which was significant in inflammatory disorders (p=0.001).48 taking COVID-19 into account as an inflammatory condition." (PMID 37575626, 2022). "We observed a direct relationship between CRP and disease severity, with asymptomatic subjects having the lowest CRP levels and severe COVID-19 patients having the highest." (PMID 36377893, 2022). "In this study, it was found that the laboratory results of the COVID-19 pregnant patients with a mortal course - profound lymphopenia, high procalcitonin, CRP, IL-6, ferritin, AST, and LDH values - were similar to the general population with a mortal course." (PMID 35592191, 2022). "IL-17 (≥138 pg.ml-1) was predictive of the need for mechanical ventilation and/or death by days 29 of admission, after adjusting for age, male gender, BMI, DM, and serum markers of COVID-19 severity such as CRP, D-dimer, and ferritin." (PMID 36136963, 2022). "As in the present study, previous studies have considered the potential capacity of the CRP/SA ratio to have greater predictive capacity than each of the components of the ratio alone in COVID-19." (PMID 35740416, 2022). "Although most patients had signs of acute inflammation (CRP, leukocytosis), these data suggest that COVID-19 patients and controls enrolled in this study had largely comparable distributions of major T-cell populations." (PMID 36052094, 2022). "Laboratory findings showed high serum ferritin, CRP and IL-6 levels and D-dimer COVID-19 patients respectively, indicative of severe COVID-19 illness." (PMID 35433146, 2022). "CRP levels in the early stage of COVID-19 have been positively correlated with the presence of lung lesions." (PMID 35935257, 2022). "Patients had to be diagnosed with the severe course of COVID-19 and the first CRP apheresis had to be performed a maximum 72 h after the onset of this severe course." (PMID 35407564, 2022). "The increase of CRP and ferritin in critically ill COVID-19 patients has been measured in various findings." (PMID 35755851, 2022). "Different biomarkers have been investigated in COVID-19 as predictor of mortality, including C-reactive protein (CRP), procalcitonin (PCT), interleukin-6 (IL-6), and soluble urokinase-type plasminogen activator receptor (suPAR)." (PMID 35859926, 2022). "Age was the strongest contributor to the progression from common type to severe type COVID-19, followed by dyspnea, CRP, IL-6 and lymphocyte count." (PMID 35037900, 2022). "Previous studies have shown that the predictors of severe prognosis in patients with COVID-19 included age, sex, CRP, LDH, lymphocyte count, D-dimer, and comorbidity (including hypertension, diabetes, cardiovascular disease, respiratory disease)." (PMID 36601398, 2022). "The influence of C-reactive protein and other inflammatory biomarkers has already been described in COVID-19 survivors." (PMID 36698837, 2022). "AST, ALT, creatinine, CRP, D-dimers were all significantly increased in higher COVID-19 class while free T3, free T4, and TSH were markedly reduced in critical cases." (PMID 35637852, 2022).